HMGA2 (high mobility group AT-hook 2)
Diseases named in the same sentence as HMGA2 in open-access papers (continued):
Sharing a sentence is not in itself a finding about the gene and the disease.
lipoma (64 papers, 2008 to 2025). A benign, usually painless, well-circumscribed lipomatous tumor composed of adipose tissue. "Genetics also play a role; some syndromes feature multiple lipomas, and the high mobility group AT-hook 2-lipoma preferred partner (HMGA2-LPP) fusion gene mutation is linked to these tumours." (PMID 41458744, 2025). "- Meningiomas: WT1- Hemangiomas: VEGFR2, Endoglin (CD105)- Melanocytic nevi: MART-1, BRAF, NRAS mutations- Lipoma: HMGA2-expressing cells." (PMID 40630962, 2025). "It is thought that two-thirds of lipoma patients have some genetic abnormalities; the HMGA2 gene (located on 12q14.3) was linked to lipoma formation as well as specific structural rearrangements in chromosomes." (PMID 40932966, 2025). "For instance, hmg-11 corresponds to the human gene HMGA2, implicated in various diseases, including lipoma, leiomyoma, and ovarian cancer." (PMID 39133097, 2024). "Gene fusions involving LPP, the gene encoding the Lipoma Preferred Partner protein, such as a recurrent HMGA2–LPP fusion have been found in multiple tumors, including lipoma, pulmonary chondroid hamartomas, and chondromas." (PMID 34711608, 2021). "Thus, although HMGA2 rearrangements appear with a high frequency in lipomas and have been implicated in lipomatous formation, the rearrangement is more likely to play a role in tumor transformation and not in building the fat depots." (PMID 33235355, 2021). "Thus, the pattern is similar to the rearrangements of HMGA2 found in other lipomas, i.e., disruption of the HMGA2 locus leaves intact exons 1–3 which encode the AT-hooks domains and separates them from the 3′-terminal part of the gene." (PMID 26202160, 2015). "This is the first time rearranged chromosomes 8 and 12 in two lipomas are found to lead to the HMGA2::CIBAR1-DT fusion transcript, though with cytogenetically different aberrations, but with the same breakpoints." (PMID 41568362, 2025). "Molecular studies of lipomas have identified chromosomal abnormalities, particularly translocations affecting chromosome 12q15 and the High-Mobility Group AT-Hook 2 (HMGA2) gene, a known regulator of adipocyte differentiation and proliferation." (PMID 41303617, 2025). "The most common chromosomal rearrangement in lipomas involves chromosomal band 12q14, targeting the high mobility group A2 (HMGA2) gene." (PMID 41568362, 2025). "The most frequent chromosome rearrangement in lipomas involves the high-mobility group AT-hook 2 gene (HMGA2), which maps to 12q14." (PMID 41568362, 2025). "LHFPL6 (tetraspanin subfamily member 6), localized to chromosome 13q, is a member of the lipoma HMGIC fusion partner gene family, which was reported as a translocation partner of the high mobility group A2 (HMGA2) gene." (PMID 41249628, 2025). "The “Mitelman Database Chromosome Aberrations and Gene Fusions in Cancer” database (last updated 10th of July 2025) displays 33 entries of “lipoma” with the involvement of the 12q14/HMGA2 gene." (PMID 41568362, 2025). "We present here, for the first time, two lipomas with two 8q22;12q14-rearrangements, leading to the formation of an HMGA2::CIBAR1-DT fusion transcript." (PMID 41568362, 2025). "Parosteal lipomas are associated with rearrangements of chromosome 12q13-15, particularly affecting HMGA2 (high-mobility group AT-hook 2)." (PMID 41561261, 2025). "The expression levels of HMGA2 were similar in lipomas and Group A tumors, but Group B tumors had higher expression than Group A tumors (fc: 4.23; p-value: 0.05)." (PMID 38769442, 2024). "These myoid hamartomas have a similar HMGA2 rearrangement as lipomas and grow on mutant mesenchymal stem cells, which can differentiate into stromal cells, adipocytes and smooth muscle cells." (PMID 39911671, 2024). "Based on the DE overlap we concluded that HMGA2-fusion lipomas are a specific molecular subtype, most probably because the adipocyte proliferation occurs through the same trigger in this subgroup." (PMID 33235355, 2021).
lipoma (continued). "These include benign tumors, like for example lipomas, breast fibroadenomas, salivary gland adenomas, hamartomas, and pituitary adenomas, where in most cases, chromosome rearrangements involving the HMGA2 gene were found." (PMID 31935816, 2020). "Molecular genetic examinations of the lipomas revealed ring/giant chromosomes and the rearrangement of the HMGA2 gene." (PMID 31282548, 2020). "The causal role of Hmga2 in the tumorigenesis was supported by the spontaneous development of lipomas and of other types of benign tumors in mice overexpressing Hmga2 or its truncated forms." (PMID 31935816, 2020). "Both pulmonary hamartomas and lipomas have a high frequency of translocations involving HMGA2, resulting in over expression of the fusion protein." (PMID 28228139, 2017). "Both pulmonary hamartomas and lipomas have a high frequency of translocations involving the HMGA2 (High Mobility Group A2) gene, resulting in over expression of the fusion protein." (PMID 28228139, 2017). "The present data nevertheless add to the evidence that expression of truncated HMGA2 is involved in the development of lipomas." (PMID 26202160, 2015). "Previous evidence also indicated that HMGA2 is fused to LIM domain containing preferred translocation partner in lipomas (LPP) gene and localized to focal adhesions as well as cell-to-cell contacts." (PMID 25868853, 2015). "Our data therefore show that a subset of soft tissue osteochondromas shares pathogenetic involvement of HMGA2 with lipomas, leiomyomas and other benign connective tissue neoplasms." (PMID 26043835, 2015). "In lipomas 3, 4 and 7 as well as the osteochondrolipoma, exon 3 of HMGA2 was fused to sequences from 18q12.3 which in lipomas 4 and 7 and the osteochondrolipoma consisted of the 3′-untranslated region of the SETBP1 gene." (PMID 26202160, 2015). "3′-RACE on lipomas (cases 3–5 and 7) and the osteochondrolipoma (case 8) amplified fragments which by Sanger sequence analysis were found to be chimeric HMGA2-cDNA fragments." (PMID 26202160, 2015). "In lipoma 5, exon 4 of HMGA2 was fused to a sequence 500 Mbp distal to HMGA2 in an intron of GRIP1 in 12q14.3." (PMID 26202160, 2015). "Most of these cases were categorized as lipomas, except for one HMGA2/LPP case, which was diagnosed as ALT/WDL." (PMID 24965044, 2014). "Although cytogenetic research shows that human lipoma formation is associated with the translocations and fusion of HMGA2-NFIB, HMGIC-LPP, and C11orf95-MKL2, there is little monogenic evidence of lipoma formation." (PMID 22623957, 2012). "HMGA2 has been found to be frequently expressed in benign mesenchymal tumors, including lipomas and leiomyomas, and to be amplified or rearranged in both well and poorly differentiated liposarcomas." (PMID 21853155, 2011). "Transgenic mice overexpressing truncated HMGA2 gene, on the other hand, develop well differentiated lipomas and abundant adipose tissue." (PMID 20576167, 2010). "In the present study, the expression of HMGA2 was increased (full-length in three and differential in two) in all five cases diagnosed as conventional lipomas with rings." (PMID 19508721, 2009). "Approximately 75% of conventional lipomas harbor chromosomal rearrangements of 12q13-15, strongly indicating the involvement of HMGA2 in these cases." (PMID 19508721, 2009). "Cytogenetic analyses of conventional lipomas have identified numerous other translocation partners to the HMGA2 locus in 12q." (PMID 19508721, 2009). "The consistently high expression of HMGA2 in conventional lipomas with ring chromosomes provides further support for the idea that these tumors belong to the same biologic entity as atypical lipomas and well-differentiated liposarcomas." (PMID 19508721, 2009). "The importance of HMGA2 expression in these lipomas and other lipomatous tumors, remains poorly investigated." (PMID 19508721, 2009).
lipoma (continued). "The notion that the molecular pathogenesis of these lipomas is different from that in 12q-positive ones was strengthened by the finding here that only one case in each group showed strong HMGA2 expression." (PMID 19508721, 2009). "RNA sequencing and RT-PCR of the two lipomas showed the presence of the HMGA2::CIBAR1-DT chimera." (PMID 41568362, 2025). "A critical area of investigation is the identification of specific genetic alterations that contribute to the development of pediatric lipomas, such as those involving the loci 12q14–15 and 6p21, which are known to lead to the overexpression of genes like HMGA2 and HMGA1." (PMID 40729232, 2025). "The primary gene that fuses with HMGA2 in lipoma is lipoma-preferred partner (3q27)." (PMID 41366963, 2025). "Dysregulation of HMGA2 expression has been implicated in various pathological conditions, including:Benign tumors: HMGA2 overexpression is frequently observed in benign tumors such as lipomas, fibroadenomas, salivary gland adenomas, hamartomas, and pituitary adenomas." (PMID 39085703, 2024). "However, four samples from Group A and four from Group B blended into the HMGA2 fusion-positive lipomas." (PMID 38769442, 2024). "One LHFP-like gene is fused to the high mobility group AT-Hook 2 (HMGA2) in lipomas." (PMID 36531047, 2022). "In sum, we show based on gene expression profiles that HMGA2-fusion lipomas are a specific subtype and while, the fusion may promote tumorigenic transformation, all lipomas share a common fat accumulation mechanism." (PMID 33235355, 2021). "To raise evidence for our hypothesis, we initially tested differential gene expression on all 15 lipoma samples and compared the results to the group with HMGA2 fusions, which had a similar genetic background." (PMID 33235355, 2021). "Of the seven lipomas with high-confidence events, four displayed HMGA2 fusions." (PMID 33235355, 2021). "Rearrangements involving HMGA2 at chromosomal region 12q14.3 have been detected in a variety of benign mesenchymal and mixed tumors including lipomas and osteochondrolipomas, chondromas of soft tissue, uterine leiomyomas, salivary gland pleomorphic adenomas, and many other entities." (PMID 33742141, 2021). "Chromosomal breaks of the HMGA2 locus have been described in several benign mesenchymal tumors including lipomas and uterine leiomyomas, and HMGA2 amplification was shown in several soft tissue malignancies including liposarcomas where it is almost always co-amplified with MDM2." (PMID 27662657, 2016). "However, it is important to note that exactly the same fragment of NFIB is fused with HMGA2 and HMGIC genes in lipoma and pleomorphic adenoma, respectively." (PMID 27533466, 2016). "In lipomas, two different HMGA2–NFIB fusion transcripts have been identified." (PMID 26857357, 2016). "In lipoma 3, exon 3 of HMGA2 was fused with a sequence 10 kbp downstream of the SETBP1 gene." (PMID 26202160, 2015). "Thus, the pattern is similar to that seen in other rearrangements of HMGA2 found in lipomas, i.e., disruption of the HMGA2 locus leaves intact exons 1–3 of the gene which encode the AT-hook domains and separates them from the 3′-terminal part of the gene." (PMID 26202160, 2015). "However, high expression levels of HMGA2 have been noted in different benign tumors such as lipomas, pleiomorphic adenomas of the salivary gland, uterine leiomyomas and lung hamartomas." (PMID 25823555, 2015). "In four lipomas and in the osteochondrolipoma (cases 3–5, 7 and 8), on the other hand, the Cq values for exons 4–5 were significantly lower than those for exons 1–2, indicating rearrangement of HMGA2." (PMID 26202160, 2015). "Moreover, transgenic mice expressing a truncated form of the HMGA2 protein develop obesity and an abnormally high prevalence of lipomas." (PMID 26202160, 2015). "Additionally, HMGA2 expression is related to a number of mesenchymal tumor cell types, including fat-cell tumors (lipomas)." (PMID 23626755, 2013).
lipoma (continued). "Cytogenetically abnormal adipocytic tumors with involvement of 8q22 and 12q14, as well as the identification of the HMGA2::CIBAR1-DT, can help subclassify these tumors, distinguishing lipomas from malignant adipocytic tumors." (PMID 41568362, 2025). "The HMGA2::CIBAR1-DT fusion, identified here for the first time, is a recurrent transcript in lipomas." (PMID 41568362, 2025). "Although a commercial HMGA2 FISH break apart probe is widely available, its utility in diagnosing ordinary lipoma is quite limited." (PMID 37131332, 2024). "HMGA2 and HMGA1 rearrangements have both been reported in multiple benign mesenchymal tumor types, including lipomas, endometrial polyps, and pulmonary chondroid hamartomas." (PMID 35822448, 2023). "For instance, 12q14–15 and 6p21 loci alterations have been shown to result in overexpression of HMGA2 and HMGA1 in pediatric lipomas." (PMID 36264345, 2022). "When we tested samples with multiple genetic backgrounds there were significantly more DE genes (DEG all samples) than when we tested only HMGA2-fusion lipomas (DEG HMGA2 fusion)." (PMID 33235355, 2021). "However, in several types of differentiated mesenchymal tumor, including lipomas, leiomyomata, pulmonary chondroid hamartomas, endometrial polyps, and soft tissue chondromas, certain genetic mechanisms enable its untimely re-expression, biologically termed HMGA2 misexpression." (PMID 32365712, 2020). "Similarly, a boy with a constitutional chromosomal rearrangement resulting in deregulation of HMGA2 displayed a number of features indicative of disturbed mesenchymal differentiation, such as marked somatic overgrowth, skeletal abnormalities and multiple lipomas." (PMID 19508721, 2009). "That HMGA2 positivity was not seen in 80 renal angiomyolipomas suggests that the lipomatous component of these tumors develops differently than in conventional lipomas." (PMID 40518465, 2025). "The gene expression profiles were compared with those in eight HMGA2 fusion-positive conventional lipomas without 12q-gain and six normal fat samples." (PMID 38769442, 2024). "A focus on the overlap allows a reduction in the search space to reveal relevant pathways dysregulated in lipomas with HMGA2 and without any fusions." (PMID 33235355, 2021). "We integrated PPIs of shared DE genes between lipomas with HMGA2 fusions and the ones without fusions to identify shared dysregulated functional modules." (PMID 33235355, 2021). "This implies that the majority of the lipomas in our samples act like no-fusion lipomas, while HMGA2-fusion lipomas can be considered a specific subtype." (PMID 33235355, 2021). "From the rest of lipoma samples, four displayed no fusions, while other four showed medium confidence fusion events, none of which involved HMGA2 gene." (PMID 33235355, 2021). "HMGA2 immunostaining is routinely used in soft tissue pathology in order to help to distinguish between normal adipose tissue (HMGA2 negative) and adipose tumor such as lipoma or liposarcomas (HMGA2 usually positive)." (PMID 28228139, 2017). "On the other hand, over-expression of a truncated HMGA2 protein lacking the acidic C-terminal tail results in a giant phenotype with multiple lipomas." (PMID 20576167, 2010). "The lack of HMGA2 expression in most cases with rearrangements of 6p21 or deletions of 13q strongly support the view that these lipomas develop through other genetic pathways." (PMID 19508721, 2009). "Based on gene expression profiles, we show that the overlap of differentially expressed (DE) genes between lipomas with HMGA2 fusions and without any fusion genes is significant, supporting our initial hypothesis." (PMID 33235355, 2021).
lipoma (continued). "Thus, we considered that lipomas with HMGA2 fusions and the ones without fusions arise through a different mechanism, but have a common dysregulation of fat accumulation, and hence the similar phenotype." (PMID 33235355, 2021). "In addition, FISH showed that the breakpoint was distal to the HMGA2 locus in lipomas 1 and 2 (data not shown)." (PMID 26202160, 2015). "Over-expression of full-length or truncated HMGA2 has been demonstrated in some lipomas without 12q-rearrangement, as well as in atypical lipomatous tumors, but no systematic analysis of the status of HMGA2 in different cytogenetic subsets of lipomas or in other lipomatous tumors has been performed." (PMID 19508721, 2009). "Furthermore, the proportion of shared DE genes among lipomas with and without HMGA2 fusion is significantly overrepresented (p-value < 0.01, Fisher’s exact test), supporting a common mechanism that may lead to the same phenotype." (PMID 33235355, 2021). "However, molecular karyotyping detected an unbalanced rearrangement of the LPP locus, not involving the HMGA2 locus, which is the most frequent translocation partner observed in benign mesenchymal tumors such as lipomas (of soft tissue as well as parosteal) and pulmonary chondroid hamartoma." (PMID 29992069, 2018). "Nor is there, as shown here, any clear-cut border between lipoma and WDLS with regard to HMGA2 status or MDM2 CN level or expression levels of these two genes, providing molecular support for the existence of an intermediary tumor type." (PMID 38769442, 2024). "Since this matched our initial hypothesis, we decided to focus our analysis on the two groups: lipomas without any fusions (DEG no-fusion) and with HMGA2 fusion." (PMID 33235355, 2021).